BAP1 (BRCA1 associated deubiquitinase 1)
Diseases named in the same sentence as BAP1 in open-access papers (continued):
Sharing a sentence is not in itself a finding about the gene and the disease.
breast carcinoma (continued). "Within the group of 46 women diagnosed with TNBC between 45 and 60 years of age but without a significant family history of breast cancer, three (6.5%) harbored mutations in ATM (n = 1), BAP1 (n = 1), or BRCA2 (n = 1)." (PMID 33302456, 2020). "Each category of breast cancer patients has some genes that are highly negatively correlated with BAP1, but there is no gene that is highly negatively correlated with BAP1 in at least two categories." (PMID 30716094, 2019). "No involvement of BAP1 in breast cancer has been found, however, and BAP1 has not been studied in the context of cancer for some time." (PMID 30395583, 2018). "In the present study, overexpression of BAP1, but not PARP3, PBRM1 or SETD2, was associated with significant (but not complete) repression of hTERT transcription within 21NT breast cancer cells." (PMID 28977912, 2017). "In addition, we have demonstrated that SETD2, BAP1, PBRM1 and PARP-3 are all down-regulated in the breast cancer cell line 21NT when compared to normal cells (HMEC), making them prime targets for tumour suppression / telomerase repression in breast cancer." (PMID 28977912, 2017). "In order to investigate the functional role of SETD2, BAP1, PBRM1 and PARP-3 in regulating hTERT transcription, we examined the effect of forced, stable overexpression of candidate genes on pre-spliced hTERT expression within 21NT breast cancer cells." (PMID 28977912, 2017). "Here we show that, in breast cancer cells, KLF5 is stabilized by the deubiquitinase (DUB) BAP1." (PMID 26419610, 2015). "Our results suggest that BAP1 and KLF5 are potential therapeutic targets for breast cancer." (PMID 26419610, 2015). "To further confirm whether BAP1 increases KLF5 protein stability, we transfected two different siRNAs targeting different regions of BAP1 into MCF10A and breast cancer cell lines (HCC1806 and HCC1937)." (PMID 26419610, 2015). "Therefore, to investigate whether the overexpression of BAP1 affects proliferation, metastasis by Med1 protein expression, cell proliferation, and invasion assays were performed in MCF7 breast cancer cells." (PMID 38708315, 2024). "For instance, BAP1 deubiquitinates and stabilizes the transcription factor KLF5, which is highly expressed in breast cancer and a potent biomarker for unfavorable prognosis in breast cancer patients, and promotes breast cancer cell proliferation, survival, and migration as well as tumor growth." (PMID 36754982, 2023). "Genetic depletion of BAP1 or inhibition of BAP1 activity by small molecule inhibitors could dramatically reduce the tumor growth of BAP1-dependent cancer, such as ASXL1-mutant leukemia, breast cancer, and SCLC." (PMID 36180891, 2022). "In conclusion, the results from the present study provide evidence to suggest that BAP1 and possibly PARP-3 repress hTERT transcription within breast cancer cells, which supports the hypothesis that multiple sequences on human chromosome 3p may be responsible for regulating hTERT transcription." (PMID 28977912, 2017). "Tumors not yet officially included in the BAP1-TPDS spectrum, but found in carriers of BAP1 PVs, are breast cancer, non-small cell lung adenocarcinoma, and neuroendocrine carcinoma." (PMID 35885614, 2022). "Interestingly, depletion of either BAP1 or KLF5 did not significantly inhibited DNA synthesis in MDA-MB-231, which is a KLF5-negative breast cancer cell line." (PMID 26419610, 2015). "BAP1 and KLF5 promote breast cancer migration, invasion and metastasis may not through p27; however, KLF5 is a transcription factor regulating numerous downstream target genes, such as FGF-BP and mPGES1." (PMID 26419610, 2015).
clear cell renal cell carcinoma (75 papers, 2014 to 2026). "In clear cell renal cell carcinoma (ccRCC), BAP1 mutations are observed in approximately 14% of cases." (PMID 41561288, 2025). "Among these, alterations in the BRCA1-associated protein 1 (BAP1) gene are frequently identified in clear cell renal cell carcinoma (ccRCC) and have emerged as adverse prognostic and predictive biomarkers." (PMID 41561288, 2025). "When we repeated similar experiments with a pair of BAP1-proficient (786-O) and BAP1-deficient clear cell renal cell carcinoma (ccRCC) cells (Umrc-6), we obtained virtually the same results." (PMID 36754982, 2023). "Nuclear loss of BAP1 protein expression has also been observed in 2 to 50% of carcinomas, including 50% of intrahepatic cholangiocarcinomas, 10 to 19% of clear cell renal cell carcinomas, and 18% of hepatocellular carcinomas among others." (PMID 35565429, 2022). "While there has been limited evidence of a link between molecular pathways, BAP1 mutation has coincided with VHL mutation in clear cell renal cell carcinoma (ccRCC)." (PMID 29085180, 2017). "BAP1 has been found to be mutated in 80% of metastatic uveal melanoma (UM), 63% of malignant pleural mesothelioma, 25% of intrahepatic cholangiocarcinoma, 15% of clear-cell renal cell carcinoma (ccRCC), and at lower frequencies in other cancers." (PMID 40754831, 2025). "In addition, 15% of patients with clear cell renal cell carcinomas (ccRCCs) were found to carry inactivating somatic BAP1 mutations, and some patients carried inactivating germline BAP1 mutations." (PMID 37009801, 2023). "In addition, the tumour-suppressive role of tumour suppressor BRCA1-associated protein 1 (BAP1) with ferroptosis has been validated in clear cell renal cell carcinoma." (PMID 36248959, 2022). "Indeed, loss function in the BAP1 gene is associated with several aggressive cancers, including clear-cell renal cell carcinomas." (PMID 34439859, 2021). "Thus, BRCA1-associated protein 1 (BAP1) is an enzyme from the ubiquitinase family whose encoding gene BAP1 is mutated in almost 10% of clear cell renal cell carcinomas (ccRCC)." (PMID 31781477, 2019). "The patient developed BAP1-inactivated melanocytic tumours, clear-cell renal cell carcinoma, and splenic hamartoma." (PMID 41712014, 2026). "Clear cell renal cell carcinoma (ccRCC) is characterized by near ubiquitous loss of VHL followed by mutations in epigenetic regulators PBRM1, SETD2, and BAP1." (PMID 39874221, 2025). "BAP1 has been reported to regulate antitumor immunity in clear cell renal cell carcinoma, although the specific mechanism remains undisclosed." (PMID 39350280, 2024). "Recent advancements in understanding clear cell renal cell carcinoma (ccRCC) have underscored the critical role of the BAP1 gene in its pathogenesis and prognosis." (PMID 38999524, 2024). "There are many mutated genes have been reported to be associated with clear cell renal cell carcinoma, including von Hippel Lindau(VHL), Polybromo 1 (PBRM1), BRCA associated protein 1 (BAP1) and SET domain containing 2 (SETD2)." (PMID 37679715, 2023). "Unfortunately, he developed hypoxic respiratory failure, and only posthumously did WES/WTS reveal pathogenic variants in BAP1 and VHL, consistent with clear cell renal cell carcinoma (ccRCC)." (PMID 37844295, 2023). "MPM has similarities to clear cell renal cell carcinoma (ccRCC), as both harbour frequent loss of function mutations in SETD2, SETD5 and BAP1, and we confirm in this study PBRM1." (PMID 35637530, 2022). "BAP1 is an important tumor suppressor involved in various biological processes and is commonly lost or inactivated in clear-cell renal cell carcinoma (ccRCC)." (PMID 35425712, 2022). "In clear cell renal cell carcinoma, BAP1 inactivation defines a specific subtype of cancer of worse prognosis." (PMID 29069806, 2017).
clear cell renal cell carcinoma (continued). "Clear cell Renal Cell Carcinoma (ccRCC) is due to loss of von Hippel–Lindau (VHL) gene and at least one out of three chromatin regulating genes BRCA1-associated protein-1 (BAP1), Polybromo-1 (PBRM1) and Set domain-containing 2 (SETD2)." (PMID 26452128, 2015). "However, in more than 90% of sporadic clear cell renal cell carcinomas, loss of chromosome 3p, which harbors tumor suppressors VHL on 3p25 and PBRM1, BAP1, and SETD2 on 3p21, is an established occurrence." (PMID 39281855, 2024). "In some solid tumors, such as advanced clear cell renal cell carcinoma, BAP1 alterations have been reported as a significant predictor of the immune microenvironment and have been associated with a longer progression-free survival (PFS) in patients when treated with ICI." (PMID 39091916, 2024). "Furthermore, BAP1 knockout in clear cell renal cell carcinoma (ccRCC) inhibits cell growth and migration and promotes the mesenchymal-epithelial transition (MET) partially by downregulating Snail and reducing Rho family GTPases activity." (PMID 37543638, 2023). "The microscopic diagnosis was a malignant epithelioid neoplasm with clear cell and rhabdoid features, and molecular testing revealed pathogenic variants in BAP1 and VHL, resulting in a post-mortem diagnosis of metastatic clear cell renal cell carcinoma (mccRCC)." (PMID 37844295, 2023). "Furthermore, the BAP1 mutant patient presented with an additional history of clear cell renal cell carcinoma, invasive ductal breast cancer and basal cell carcinoma." (PMID 32354124, 2020). "Similar to benign renal cysts, hemangioblastomas rarely demonstrate aggressive malignant features, and we did not detect additional clonal genetic drivers in hemangioblastomas, including other candidate genomic loci on chromosome 3p of BAP1, SETD2, and PBRM1 implicated in clear cell renal carcinoma." (PMID 25589003, 2014). "Whereas VHL inactivation is a primary event in clear cell renal cell carcinoma (ccRCC), the precise mechanism(s) of how this interacts with the secondary mutations in tumor suppressor genes, including PBRM1, KDM5C/JARID1C, SETD2, and/or BAP1, remains unclear." (PMID 30355451, 2018). "Combined analysis of three recent large-scale clear cell renal cell carcinoma (CCRCC) mutation sequencing projects identified a significantly increased mutation frequency of PBRM1 and the X chromosome encoded KDM5C in tumors from male patients and BAP1 in tumors from female patients." (PMID 26484545, 2015). "Furthermore, BAP1 loss is not specific for PM, and it may be seen in clear cell renal carcinoma, thymic carcinoma, and melanoma." (PMID 40361508, 2025). "PBRM1, SETD2, and BAP1 were previously known HNSC genes and recently found to be altered in clear cell renal cell carcinoma." (PMID 28938536, 2017).
meningioma (64 papers, 2016 to 2026). A generally slow growing tumor attached to the dura mater. "The aim of this study was to investigate the association, clinical, and pathologic characteristics of meningioma in BAP1-TPDS." (PMID 41670784, 2026). "BAP1 (BRCA1-associated protein 1) is a tumor-suppressor gene whose loss has been associated with aggressive clinical behavior and increased metastatic potential in meningiomas." (PMID 41552249, 2025). "Meningioma metastasis remains exceedingly rare, but risk increases with higher grade, recurrence, and molecular alterations such as BAP1 loss or NF2 inactivation." (PMID 41552249, 2025). "PBRM1 mutations are relatively uncommon in meningiomas, but when present, they are associated with papillary subtypes and often have overlapping BAP1 mutations." (PMID 41199851, 2025). "Of note, hepatocellular carcinoma, cholangiocarcinoma and meningioma have also been associated with the BAP1-TPDS." (PMID 38785832, 2024). "While most meningiomas are sporadic, they can occur in genetic syndromes, including neurofibromatosis type 2, BAP1 tumor predisposition syndrome, and Gorlin syndrome." (PMID 38730704, 2024). "Variants in SMARCB1 and SMARCE1, components of the SWI/SNF chromatin remodeling complex, are enriched in higher-grade meningiomas, and BAP1 alterations are associated with rhabdoid morphology, though the predictive ability of these events is not established." (PMID 38730704, 2024). "Other cancers proposed to be associated with BAP1 GPV include meningioma, hepatocellular carcinoma, cutaneous basal cell cancer and cholangiocarcinoma." (PMID 37607989, 2023). "The CDKN2A and BAP1 mutation seem to be associated with aggressive forms of meningioma, while the SMASRCE1 mutation is attributable to the onset of spinal meningiomas." (PMID 37760490, 2023). "BAP1 loss on IHC was more common in histologically rhabdoid and papillary meningiomas (WHO grade 3), although more cases are being reported in exclusion of these histological subtypes." (PMID 36840836, 2023). "Somatic BAP1 mutations are frequently an underlying genomic aberration in rhabdoid meningiomas and are associated with a more clinically aggressive meningioma, resulting in multiple recurrences and shortened OS." (PMID 37010677, 2023). "Germline BAP1 mutations have also been identified, increasing the hereditary risk of meningiomas and other cancers including uveal melanoma, cutaneous melanoma, and renal cell carcinoma." (PMID 37010677, 2023). "Only one patient (case #4) harbored a germline BAP1 mutation in both intracranial and distant meningioma manifestations, with an additional PIK3CA mutation." (PMID 36641486, 2023). "More recently additional tumour types including meningioma, cholangiocarcinoma and hepatocellular carcinoma have been suggested as possible associations with BAP1-TPDS." (PMID 37607989, 2023). "More recently, other tumors, such as basal cell carcinoma (BCC), cholangiocarcinoma, and meningioma, have been associated with BAP1-TPDS, albeit characterized by a much lower incidence." (PMID 35885614, 2022). "Inactivation of BAP1 has been seen in a subset of highly aggressive rhabdoid meningiomas and are associated with very poor clinical outcomes, multiple recurrences, and significantly shortened overall survival." (PMID 33801089, 2021). "BAP1 mutations are specifically associated with meningiomas with rhabdoid morphology and can occur in both the adult and pediatric population." (PMID 33346248, 2020). "No case of cholangiocarcinoma was reported in our patient population and meningioma was present in one proven carrier of a pathogenic BAP1 gene (1/72, 1.4%), who developed a vestibular schwannoma as well as an UM later in life." (PMID 31382694, 2019). "Germline BAP1 mutations have been noted in several of these and other cancers such as meningioma, paraganglioma, basal cell carcinoma, ovarian cancers, and neuroendocrine tumors." (PMID 28122578, 2017).
meningioma (continued). "Additionally, we conducted a literature review of meningioma case studies for individuals with germline BAP1 (P/LP) variants." (PMID 41670784, 2026). "Similarly, BAP1 loss defines a biologically distinct and clinically aggressive subset of meningiomas characterized by epithelioid morphology, cytokeratin expression, and a specific methylation signature." (PMID 41552249, 2025). "Our results suggest that molecular diagnostics allow an accurate discrimination of true metastatic lesions and might indicate an involvement of BAP1 loss-of-function in metastatic spread of meningiomas." (PMID 36641486, 2023). "As the proband’s daughter (III-2) had been diagnosed with meningioma—in 2017, at the age of 48—we sought to determine whether this tumor also displayed loss of BAP1 protein expression." (PMID 35885614, 2022). "Furthermore, 8% harbored mutations in TERT, CDKN2A/B, or BAP1 of which 6% occurred in grade 1 meningiomas." (PMID 35299730, 2022). "Inactivating BAP1 mutations have been associated with inferior outcomes in rhabdoid meningioma and meningioma with rhabdoid features, and routine tumor testing for this mutation may aid prognostication in lower grade tumors with rhabdoid features." (PMID 34504799, 2021). "Germline BAP1-mutant meningiomas arise more commonly than in somatic mutations." (PMID 33801089, 2021). "Indeed, inactivation of the tumor suppressor gene BAP1 has been linked to aggressive meningiomas with rhabdoid histo-morphology and was associated with a shorter progression-free survival." (PMID 33087175, 2020). "For patients with aggressive rhabdoid meningioma harboring BAP1 mutations, Tazemetostat, which awaits FDA approval for other tumor types, may prove useful." (PMID 31970090, 2019). "In addition, BAP1-deficient meningiomas represent a unique molecular class associated with early relapse and may be linked to hereditary tumor syndromes." (PMID 41552249, 2025). "Moreover, loss of BAP1 gene expression also appears to be involved in familial meningiomas." (PMID 38785832, 2024). "Moreover, the identification of the inactivation of BAP1 in rhabdoid meningiomas may differentiate between aggressive and less-aggressive rhabdoid-appearing meningiomas, where the loss of BAP1 protein expression indicates early tumor recurrence." (PMID 35565385, 2022). "However, to our best knowledge, we present the first report of an inherited BAP1 inactivating mutation identified after several generations of a family presented with meningioma with rhabdoid features instead of with previously documented BAP1 loss-associated cancers." (PMID 34504799, 2021). "Thus, use of this drug in meningioma patients with BAP1 driver mutations may prove clinically beneficial in future trials." (PMID 31970090, 2019). "CONCLUSION: This study provides additional evidence that high-grade brain and spinal meningiomas are part of the clinical spectrum of BAP1-TPDS." (PMID 41670784, 2026). "Mutations in SMARCE1 (SWI/SNF-related matrix-associated actin-dependent regulator of chromatin subfamily B member 1), BAP1 (BRCA1 associated protein-1), and PBRM1 are associated with different meningioma histologic subtypes." (PMID 38695575, 2024). "Recent studies have also illustrated the mutations in TERT promoter regions in grade III meningiomas, along with alterations in SMARCE1 and BAP1 that have been reported widely in clear cell and the rhabdoid subset of meningiomas." (PMID 37770851, 2023). "Larger cohorts, most likely from multicenter studies are necessary to evaluate the role of BAP-1 alterations to further understand the metastatic spread in meningiomas." (PMID 36641486, 2023). "Additional TERT promoter mutation and homozygous CDKN2A/B loss have similarly been linked to more aggressive meningiomas In contrast, homozygous CDKN2A/B loss, TERT promoter mutations or alterations in BAP1 are associated with more aggressive clinical courses." (PMID 36641486, 2023).